RNU6-636P (RNA, U6 small nuclear 636, pseudogene)
Gene: Small nuclear RNA gene on chromosome 1 (37,203,610 to 37,203,716, forward strand). Ensembl gene ENSG00000207328.
Homologues: Orthologues: chimpanzee U6 (98% identical), mouse Gm25061 (85% identical), pig U6 (81% identical), rat LOC120099424 (73% identical). Paralogues in human: RNU6-890P (87% identical), RNU6-28P (85% identical), RNU6-38P (85% identical), RNU6-480P (85% identical), RNU6-774P (85% identical), RNU6-16P (84% identical), RNU6-1 (83% identical), RNU6-1005P (83% identical), RNU6-1145P (83% identical), RNU6-1316P (83% identical), RNU6-2 (83% identical), RNU6-21P (83% identical), and 1284 more.